AR (androgen receptor)
Diseases named in the same sentence as AR in open-access papers (continued):
Sharing a sentence is not in itself a finding about the gene and the disease.
prostate carcinoma (continued). "Androgen receptor signaling is crucial for prostate cancer growth and is positively regulated in part by intratumoral CYP3A5." (PMID 32316460, 2020). "The significance of the AR in prostate cancer is evident from the involvement of the AR in a range of metabolic processes, both anabolic and catabolic pathways, to promote the survival of prostate cancer cells." (PMID 32927797, 2020). "As to the intervention means of prostate cancer, androgen receptor (AR) targeting is an important therapeutic strategy and the next-generation androgen receptor (AR) pathway inhibitors (ARPIs) prolong the survival of patients." (PMID 33029516, 2020). "In this study, we propose to inhibit SRF, a co-regulator of AR in prostate cancer, as a possible way to overcome resistance to enzalutamide." (PMID 33260953, 2020). "miR-30b-3p and miR-30d-5p can be direct regulators of androgen receptor signaling in prostate cancer, and inhibition of miR-30b-3p and miR-30d-5p can increase androgen receptor (AR) expression and promote androgen-independent cell growth." (PMID 32117463, 2020). "In prostate cancer, AR activated the expression of several lncRNAs, such as ARLNC1, PCGEM1, and SOCS2-AS1, via binding to the androgen response element (ARE) sites in the lncRNA locus and promoting tumor progression." (PMID 32661324, 2020). "Because anti-cancer drugs targeting AR have been well-characterized in prostate cancer, existing drugs can be explored as potential treatment options for other AR-positive cancers as well." (PMID 32781788, 2020). "We then focused on the molecular functions of AR-regulated lncRNAs since the importance of lncRNAs was proposed in prostate cancer progression." (PMID 32704143, 2020). "Apart from AR signaling, metabolic reprogramming in prostate cancer cells can promote cancer development." (PMID 32093357, 2020). "Growing evidence demonstrates that the AR and Tip60 modulate key metabolic processes to promote the survival of prostate cancer cells, in addition to their classical roles." (PMID 32927797, 2020). "Prostate-specific antigen (PSA) is one of the genes regulated by AR and is considered the most sensitive biomarker for confirming the existence of prostatic disease and prostate cancer." (PMID 32972001, 2020). "Prostate cancer is initially androgen-dependent, but the effectiveness of androgen receptor (AR) inhibitors in recurrent disease is variable." (PMID 33029258, 2020). "Let-7c was reported to function as tumor suppressor in prostate cancer by regulating AR transcription via MYC." (PMID 32974144, 2020). "The majority of deaths from prostate cancer is due to advanced-stage metastatic spread dependent on the androgen receptor (AR)." (PMID 35582225, 2020). "Selective androgen receptor modulators (SARMs) that function as AR antagonists in specific cell types including prostate cancer cells, and selective androgen receptor degraders or down-regulators (SARDs) are being studied for clinical application." (PMID 32106418, 2020). "Previous studies have revealed that miR-30b-3p is downregulated in primary prostate cancer (PCa) and metastatic castration resistant PCa and can directly inhibit androgen receptor and PCa cell proliferation." (PMID 32833670, 2020). "To that extent, we found that the SART3, a RNA binding protein and a binding partner of AR, was predicted to be enriched downstream of AR-enhanced exons and underrepresented in the same region of AR-excluded exons in prostate cancer cells." (PMID 32820253, 2020). "In prostate cancer cells, IL-6 dependent interplay with AR interferes with the PKA/PKC/MAPK pathway and IL-8 has been shown to promote their AR dependent growth and activation independent of androgens." (PMID 32849531, 2020). "As for ERG, it synergistically regulates by physically interacting with prostate-cancer-specific regulators AR, HOXB13, and FOXA1." (PMID 33299103, 2020).
prostate carcinoma (continued). "In order to investigate the impact of the androgen axis on heat sensitivity, we next sought to test the impact of AR inhibition and 5α-Reductase inhibition on heat sensitivity of androgen-dependent prostate cancer cells." (PMID 33316876, 2020). "MDV3100 (Enzalutamide) is authorized as the anti-prostate cancer drug, and inhibits nuclear translocation of AR, and coactivator recruitment." (PMID 32269992, 2020). "Prostate cancer is driven by the androgen receptor (AR)-regulated gene expression that is initiated by the binding of androgen to the AR." (PMID 31952332, 2020). "The crucial role of androgen receptor (AR) in prostate cancer development is well documented, and its inhibition is a mainstay of prostate cancer treatment." (PMID 30838415, 2019). "Resistance to androgen receptor (AR)-targeted therapies in prostate cancer (PC) is a major clinical problem." (PMID 31006810, 2019). "Our previous results indicated that CDK5 increases prostate cancer growth through the activation of AR protein and the CDK5–p35/AR complex translocates into the nucleus and promotes prostate cancer growth." (PMID 31395805, 2019). "Current treatment for advanced prostate cancer relies on taxane-based therapy and on new generation antiandrogen drugs (abiraterone, enzalutamide) able to inhibit the activity of the AR." (PMID 31284411, 2019). "Androgen receptor (AR), a steroid receptor transcription factor, plays a pivotal role in driving prostate cancer (PCa) initiation and progression." (PMID 30718921, 2019). "While the involvement of abnormal AR signalling in prostate cancer is well established, there is growing evidence that it also plays a role in various other malignancies—specifically breast and lung cancer." (PMID 30979711, 2019). "Bicalutamide and darolutamide but not apalutamide treatment significantly upregulated NR3C1 and SLC7A11 expression, demonstrating that AR antagonist-induced transcription in prostate cancer cells is not limited to a single AR antagonist." (PMID 31501863, 2019). "In this review, we will discuss the evidences supporting a role for RSV as modulator of ER and AR in breast and prostate cancer, respectively." (PMID 30832393, 2019). "More recently, it was reported the very frequent occurrence of amplification of an enhancer region of the AR, detected in virtually all prostate cancers postprogression." (PMID 31366128, 2019). "Among those, we found that enhancer–promoter loops for the AR gene are specific to the prostate cancer cells." (PMID 31515496, 2019). "The present study demonstrates for the first time the feasibility to detect the two main AR modifications in CTCs of patients with advanced prostate cancer in a single blood tube." (PMID 31289619, 2019). "Although the majority of studies are focused on the role of AR signaling, compelling evidence has shown that estrogens and their receptors control prostate cancer initiation and progression through a still debated mechanism." (PMID 31548498, 2019). "Cancer genomic analysis using 13 multidimensional prostate cancer data sets showed that significantly higher genetic alterations were observed for AR (19%) and MCL1 (5%) genes among the CGS." (PMID 31816863, 2019). "In summary, our results demonstrate the ability to reliably characterize the two main AR-modifications in CTCs of patients with advanced prostate cancer in a single-tube assay." (PMID 31289619, 2019). "AR is usually expressed in most of the prostate cancer cells and plays differential roles in cell growth, proliferation and development of both androgen dependent and androgen independent cancer." (PMID 32010628, 2019). "The AR remains an important driver in advanced prostate cancer, however, responses to AR‐targeting therapies in CRPC is limited, with most patients experiencing limited therapeutic responses and rapid disease progression." (PMID 31228231, 2019).
prostate carcinoma (continued). "PARP1 inhibition diminished AR activity and sensitized prostate cancer cells to both DNA damage and androgen depletion." (PMID 31404966, 2019). "AR signalling is central to the prostate cancer development, thus the primary treatment of prostate cancer is androgen deprivation by chemical or surgical castration." (PMID 30832393, 2019). "Nevertheless, the fact that IRC117539 induces almost total AR clearance ex vivo is remarkable and reflected in massive and selective death of prostate cancer cells that are exclusively addicted to AR." (PMID 31431473, 2019). "In this review, we summarize the roles of NRs in prostate cancer according to the classification into subfamilies with a focus on NRs other than AR." (PMID 31212954, 2019). "The activity of these genes, referred to as “androgen receptor output”, varies between different patients with prostate cancer and even between different cells from a single patient’s tumor." (PMID 30644358, 2019). "Amongst the key data supporting this proposed model, we find that ESRP2 is a direct and early target for transcriptional activation by the AR in prostate cancer cells." (PMID 31478829, 2019). "This study investigated the mechanism by which CWP232291 induces apoptosis and the effect of CWP232291 on WNT/β-catenin and AR signaling in prostate cancer cells." (PMID 31387608, 2019). "In 2011, Carver at el studied the cross-talk between AR and PI3K/AKT pathways in PTEN-deficient prostate cancer." (PMID 34926721, 2019). "Because AR signaling plays pivotal roles in prostate cancer, AR targeting therapies are widely used for prostate cancer treatment." (PMID 31664946, 2019). "In this study, we examined the role of ERβ and ZFHX3 in and their interaction as a mechanism for the regulation of proliferation of AR-positive prostate cancer cells." (PMID 30979864, 2019). "Enzalutamide, a second-generation androgen receptor (AR) antagonist, has demonstrated clinical benefit in men with prostate cancer." (PMID 31501863, 2019). "The growth and survival of prostate cancer cells rely on androgen receptor (AR), which is activated by androgens (reviewed in Ref." (PMID 30905075, 2019). "The androgen receptor (AR) plays key roles in the development of prostate tissue and the development and progression of prostate cancer (PC)." (PMID 31520575, 2019). "Primary prostate cancer (PCa) is hormone-driven and mediated by the ligand-activated nuclear receptor and transcription factor AR." (PMID 31771198, 2019). "Androgen receptor (AR) targeted therapy is highly effective in advanced prostate cancer but is complicated by the emergence of drug resistance, called castration-resistant prostate cancer (CRPC)." (PMID 30644358, 2019). "The results indicated that overexpression of CDK5 and p35 decelerates the degradation of AR protein in prostate cancer cells while CDK5 overexpression cannot help the degradation of S81A mutant AR." (PMID 31395805, 2019). "Analogous to this, AR in prostate cancer cells is confined in the cytosol prior to testosterone binding." (PMID 30620009, 2019). "Since androgen ablation was demonstrated as efficient therapy for advanced prostate cancer substantial efforts have been focused on development of drugs that target androgen receptor (AR) signaling." (PMID 30871232, 2019). "By siRNA-mediated knockdown of AR in prostate cancer cell lines, miR-32 was found to be upregulated and to enhance NSE activity, thereby promoting neuroendocrine differentiation of the prostate cancer cells." (PMID 31744106, 2019). "Our results demonstrated that Roscovitine treatment significantly suppressed AR protein activation, AR subcellular translocation, transcriptional activity, and cell proliferation in prostate cancer cells, which was strongly correlated to CDK5 actions." (PMID 31395805, 2019).
prostate carcinoma (continued). "RORγ drives AR expression while selective RORγ antagonists inhibit AR expression and prostate tumor growth, suggesting an oncogenic role for RORγ and its potential as a therapeutic target in prostate cancer." (PMID 31212954, 2019). "While the role of the AR pathway has been well-established in prostate cancer, the role of the WNT signaling pathway is less clear." (PMID 31434336, 2019). "The cell autonomous AR signaling occurring in prostate cancer seems to be mediated by autocrine release of androgens by AR-positive tumor cells and by acquisition of intracellular activation pathways." (PMID 31366128, 2019). "One is the new anti-androgen enzalutamide (or MDV-3100), which was developed for the irreversible blockade of androgen–AR interactions, and which has already been proven to offer a survival benefit to relapsed prostate cancer patients." (PMID 30986993, 2019). "In their trial on the cell cycle dependent regulation of AR in prostate cancer cell lines, a cytoplasmic localization of the receptor was shown to be characteristic of mitotic cells." (PMID 31718606, 2019). "Since then, the AR has remained the primary target for systemic therapeutics for prostate cancer patients." (PMID 30838415, 2019). "Mutagenesis experiments have identified an additional role for the LBD in AR nuclear export, as a 75-amino-acid region (residues 743-817) is both necessary and sufficient for AR nuclear export in a PC3 prostate cancer cell model." (PMID 31686397, 2019). "Treatment of 22Rv1 prostate cancer cells with Sema4D or dihydrotestosterone (an AR agonist) resulted in a significant increase in endogenous AR in the nucleus, compared to vehicle control." (PMID 31861264, 2019). "Analysis of primary prostate cancer samples shows that translocation events leading to fusions of an ETS family member to an AR-driven promoter are found in about half of the patients." (PMID 31200487, 2019). "Here, we address the topic of intra-tumoral heterogeneity in AR transcriptional output, for which we find substantial evidence in prostate cancer cell lines and in primary prostate tumors." (PMID 30644358, 2019). "TRIM24 protein augments AR signaling and promotes prostate cancer proliferation under low androgen conditions." (PMID 31366128, 2019). "Androgens and the Androgen Receptor (AR) signalling pathway play a key role in prostate cancer pathophysiology." (PMID 31760582, 2019). "The combination of an ATR inhibitor and an AR-antagonist has recently shown improved efficacy in a prostate cancer xenograft model." (PMID 31242618, 2019). "Enzalutamide is considered as a potent AR signaling inhibitor approved for the therapy in men with metastatic castration-resistant prostate cancer." (PMID 31126320, 2019). "Androgens and androgen receptor (AR) function in the development and progression of prostate cancer." (PMID 31100782, 2019). "Androgen/androgen receptor (AR) signaling is a significant driver of prostate cancer progression, therefore androgen-deprivation therapy (ADT) is often used as a standard form of treatment for advanced and metastatic prostate cancer patients." (PMID 30871130, 2019). "The serum levels of the prostate specific antigen (PSA) protein increase in untreated castration resistant prostate cancer (CRPC) patients as reactivation of AR activity in prostate cancer cells drives the transcription of AR target genes such as PSA." (PMID 31819114, 2019). "Recent studies have supported the link between AR signaling and lipid biosynthesis in prostate cancer cells." (PMID 31366128, 2019). "Intriguingly, a genetic polymorphism in MR was associated with prognosis in androgen-deprivation therapy for metastatic prostate cancer, suggesting that MR plays a key role in the resistance of prostate cancer to AR axis-targeting therapies." (PMID 31212954, 2019).
prostate carcinoma (continued). "Another important component of bone marrow is mesenchymal stem cells (MSCs), which were found to increase the prostate cancer cell metastatic ability through suppression of AR signaling and also to affect prostate cancer cells homing to the bone marrow." (PMID 31753020, 2019). "A recent study also demonstrated that RT results in androgen receptor (AR) upregulation in various in vitro and in vivo prostate cancer models, providing further evidence of synergism between ADT and RT." (PMID 30973905, 2019). "AR is a leading player in prostate cancer pathogenesis and exerts its functional effect mainly through genomic pathway." (PMID 31212954, 2019). "The AR pathway has been successfully addressed in the treatment of early and late-stage prostate cancer for many years, originally with surgical or chemical castration and later with AR antagonists and androgen synthesis inhibitors." (PMID 31200487, 2019). "Although inhibition of the androgen–androgen receptor (AR) axis effectively represses the growth of prostate cancer, most of all cases eventually become castration-resistant prostate cancers (CRPCs)." (PMID 30939845, 2019). "We found that CTCF-binding sites are located at the prostate cancer-specific TAD boundaries for AR loci both in normal and cancer cells." (PMID 31515496, 2019). "In prostate cancer, specifically, the anti-tumor activity of BET bromodomain inhibition has been principally linked to suppression of androgen receptor (AR) function." (PMID 30846826, 2019). "MPC is transcriptionally regulated by AR in prostate cancer cells and its inhibition restricts tumor cell proliferation and metabolic flow through lipogenesis and oxidative phosphorylation." (PMID 31366128, 2019). "In our previous study, Cryptotanshinone and Baicalein, structures of which are similar to DHT, were found to suppress androgen receptor-mediated growth in androgen-dependent prostate cancer cells." (PMID 31871879, 2019). "In fact, blocking Bcl-XL expression in prostate cancer cells decreased cell proliferation and silencing the AR gene in prostate cancer cells significantly reduced Bcl-XL expression and increased apoptosis." (PMID 31671779, 2019). "We identified the prostate cancer CTCs based on their positive immunostaining for androgen receptor (AR)." (PMID 31416141, 2019). "The main way that prostate cancers become resistant to antiandrogen drugs is by making more of the androgen receptor." (PMID 30644358, 2019). "Androgen/AR signaling is still considered an important factor for prostate cancer cell survival following CRPC progression, while recent studies have reported dichotomic roles for androgen/AR signaling." (PMID 30871130, 2019). "This is particularly important for the cases of hormone-dependent breast and prostate cancers, where ERα and AR are the main targets for anti-hormonal therapy." (PMID 30717249, 2019). "Together, our findings reveal a mechanistic link between TLE3 and GR-mediated resistance to AR inhibitors in human prostate cancer." (PMID 31855178, 2019). "Meanwhile, the knockdown of AR expression had a marked effect on AR-mediated transcription and cell growth in the androgen-insensitive (androgen-independent) prostate cancer cell lines." (PMID 31137764, 2019). "We used LNCaP, an androgen-sensitive prostate cancer cell line, to confirm that PA inhibits the AR pathway in vitro." (PMID 31615010, 2019). "Strikingly, prostate cancer cells with high levels of AR are rendered hypersensitive to even minimal amounts of circulating testosterone." (PMID 31431473, 2019). "Prostate cancer (PCa) is the most frequent cancer in North American men and PCa cells rely on the androgen receptor (AR) for growth and survival." (PMID 31485472, 2019). "Immunoblotting results indicated that calpeptin (40 μM for 24 h) effectively inhibited calpain activity, and protected filamin A and androgen receptor from cleavage by calpain in human prostate cancer cell lines PC-3." (PMID 30448882, 2019).